CD4 (CD4 molecule)
Diseases named in the same sentence as CD4 in open-access papers (continued):
Sharing a sentence is not in itself a finding about the gene and the disease.
infection (continued). "The first assumption is likely to be overconservative, given that per-cell CXCR4 density on activated memory CD4+ T cells is lower than on naive CD4+ T cells, so that X4 infection of activated memory CD4+ T cells should not be as efficient as X4 infection of activated naive CD4+ T cells." (PMID 22866173, 2012). "Besides the infection of CD4+ T cells and macrophages by cell-free virions and donor-infected cells, DC-SIGN-directed capture of HIV-1 and transmission to CD4+ T lymphocytes is considered as an important avenue of primary infection of women exposed to HIV-1 through sexual intercourse." (PMID 22851920, 2012). "To unequivocally rule out this population is a result of CD4 T cell Gag acquisition independent of infection, we incubated DC-T cell co-cultures with 10 μM of AZT and confirmed the appearance of the p24/Capsid high population to be a result of productive infection." (PMID 22685410, 2012). "Thus, using CD4<200 cells/μl as a surrogate of false positivity, the FPR for recent infections was 3.86%, and adding VL<400 copies/mL to the definition, the FPR for recent infections was 4.67%." (PMID 22363755, 2012). "The broadly neutralizing mAbs 2G12 (gp120-specific) and Sim4 (CD4-specific) also inhibited infection, indicating that this infection protocol does not alter the physiological HIV-1 entry pathway mediated by envelope-receptor interaction by inducing non-specific membrane fusion events." (PMID 23028850, 2012). "However, when co-cultured with HIV-1-infected autologous DCs, there was no significant trend for infection- or Nef-dependent proliferation of resting CD4+ T cells." (PMID 22479639, 2012). "Finally, we found that both CD4+ and CD8+ cells are the primary producers of IFN-γand that γδTCR+ cells and NK cells make a minimal contribution toward production of this cytokine throughout infection." (PMID 22428026, 2012). "The virus infects CD4+ T cells, CD8+ T cells, B cells, macrophages and fibroblasts; this diversity of infection occurs possibly because of the ubiquitous distribution of its hypothesized receptors (glucose transporter 1, heparan sulfate and proteoglycans and neuropilin-1)." (PMID 23110561, 2012). "However, the change in the proportion of CD8+ T cells was not as significant as that seen in CD4+ T cells before and post infection with schistosomes in yellow cattle." (PMID 22414188, 2012). "Moreover, cell infection was not due to viral particles shed into the supernatant since virus was undetectable in the absence of CD4+ T lymphocytes." (PMID 22808239, 2012). "For a more precise interpretation of these data, we evaluated the specific migration of CD4/CD8-defined thymocyte subsets (expressed as percentage of input for each subset), taking into account that the relative amounts of distinct CD4/CD8-defined thymocyte subpopulations changed after infection." (PMID 22461911, 2012). "Other markers produced by functionally active lymphocytes such as soluble CD4 (sCD4), soluble CD8 (sCD8), β2-microglobulin (β2-M), and soluble class I antigens (sHLA-I) are released, in the sera of patients with acute BF, and correlate with the evolution of infection." (PMID 21912565, 2012). "After intravenous infection, CD4 T cells responding to each of these antigens expressed T-bet and produced IFN-γ following in vitro restimulation, thus Salmonella generates distinct antigen-specific Th1 cell populations that appear at different stages of infection." (PMID 22275869, 2012). "However, as both IL-7Rα449F and Dmu mice have reduced number of baseline CD4 and CD8 T cells in the spleen and lung prior to infection we examined the frequency of CD8 T cells that recognize the virus with MHC class I tetramers containing immunodominant viral epitopes NP366–374 and PA224–233." (PMID 23189186, 2012).
infection (continued). "To functionally assess the effect of Nef expression on resting CD4+ T cell activation, we performed a flow cytometry based T-cell proliferation assay using carboxyfluorescein diacetate succinimidyl ester (CFSE) labeling and also measured p24 production over a period of 7 days of infection." (PMID 22479639, 2012). "However, none of the recovered donor CD4 T cells were positive for GFP in either NOD or NODTGFβ recipients indicating that infection in the local presence of TGF-β does not induce Foxp3 expression in CD4 T cells." (PMID 22355341, 2012). "The protective effects of IL-7 on memory CD4+ T cells were not sustained after treatment interruption as shown by the significant decline of all three subpopulations, compared to baseline, on day 62 post-infection." (PMID 22511868, 2012). "Firstly, our modelling did not include additional cell populations such as macrophages that might contribute to increased selection for X4 virus at later stages of the infection when total CD4+ T cell counts are low, since macrophages provide an additional source of CXCR4-CD4 complexes." (PMID 22866173, 2012). "Maintenance of relatively higher expression levels of TGF-β in the chronic phase of the infection in aly/aly mice may be related to the generation and maintenance of CD4+Foxp3+ Tregs rather than the inhibition of granuloma maturation." (PMID 22928057, 2012). "The chronic phase is clinically latent, but eventually without therapeutic intervention, the infection progresses to the symptomatic phase characterized by increased viral load and rapidly decreasing CD4+ T cell and also CD8+ T cell levels, making patients prone to opportunistic infections." (PMID 22754568, 2012). "Results showed that a lower increase of log TRECs/mL from T0 to T72 is to be expected in the presence of a higher basal log TRECs/mL or of a higher CD4+/CD8+ ratio at T0, and that greater log KRECs reductions could be ascribed to longer infection duration before therapy initiation." (PMID 22591651, 2012). "However, DCs can also transmit virus to CD4+ T cells (trans-infection), without being productively infected." (PMID 22912740, 2012). "Similarly, latent MCMV-infection did not measurably influence the total number of naïve CD4+ T cells in the blood or in different lymphoid and non-lymphoid organs." (PMID 22916013, 2012). "In particular in CD4+ T-lymphocytes, the efficacy of HIV-1 replication is tightly coupled to the activation state of these target cells: while HIV-1 readily undergoes multiple rounds of replication in activated memory CD4+ T-cells, resting helper T-cells are refractory to productive infection." (PMID 23227982, 2012). "Double negative (CD4–/CD8–) NKT cells was enhanced after infection in both groups of mice (p<0.05)." (PMID 22457760, 2012). "However, as activated/effector CD4+ and CD8+ T cells (defined by CD44 and CD62L expression) appeared in elevated numbers, it is possible that the remaining anti-CD25 antibodies were still blocking CD25 epitopes on T cells at week 2 of infection." (PMID 23226464, 2012). "However, in the first 5 days of infection no evident killing of primary CD4+ T cells is shown by comparing the infected SupT1/PBMC cocultures with the uninfected SupT1/PBMC cocultures." (PMID 22701517, 2012). "Although we found that resting CD4+T cells in our model do not support productive infection, calling these cells latent may still seem controversial." (PMID 22911005, 2012). "Notably, activated CD8 T cells expressed more CD48 than their activated CD4 T cell counterparts during LCMV clone 13 infection, and in the absence of 2B4, NK cells displayed an enhanced ability to lyse activated CD8 T cells." (PMID 23248626, 2012). "This provides for increased numbers of activated CD4+ T cells for productive infection by X4 virus, but not R5 virus, since activated naive CD4+ T cells exhibit high expression of the CXCR4 chemokine receptor on the cell surface, with no/negligible CCR5 expression." (PMID 22866173, 2012).
infection (continued). "In addition, N1N2ΔCD4Cre mice do not control infection revealing that N3 and N4 are not functionally redundant in driving IFNγ secretion by CD4+ T cells." (PMID 22396647, 2012). "The CA-074Me treatment did not affect the CD4-dependent mNDK vector infection in 293T/CD4 cells." (PMID 21541353, 2011). "Thus our results suggest that vaccination induces CD4+ T-cell population and maintains the same even after infection, without altering the CD8+ T-lymphocyte levels." (PMID 21347426, 2011). "Previous calculations, based on Tat transactivation of the viral LTR alone in HeLa-CD4-LTR-β-Gal indicator cells, estimated that total transcription from unintegrated templates following infection with integrase defective virus was about 10% of that for productive infections." (PMID 21722380, 2011). "In order to determine if spinoculation was masking subtle differences in the susceptibility to infection, we infected CD4+ T cells with CXCR4-tropic virus without spinoculation and again found that CD4+ T cells from patient 169 were fully susceptible to infection." (PMID 22141397, 2011). "Furthermore, it increased the relative and absolute numbers of LCMV-specific CD4+ T cells producing TNFα on day 11, but not on day 8 after infection." (PMID 21966366, 2011). "CD4+ T cells have profound effect on protective immunity as they assist the B-cells to produce more antibodies and in the generation of Salmonella specific CD8+ T cells.We also observed that the numbers of CD4+ T cells were slightly reduced with the STM-WT infection." (PMID 21347426, 2011). "Because the endosome acidification inhibitors much less efficiently attenuated cathepsin B activity than CA-074Me, the endosome acidification inhibitors could not enhance the CD4-independent infection." (PMID 21541353, 2011). "The GFP+ CD4+ CD62Llow T cells increased significantly in both strains in response to infection, but despite the lack of eosinophils in ΔdblGATA-1 mice, we detected equal numbers of GFP+ CD4+ CD62Llow T cells per 106 MLN cells in 4get and ΔdblGATA-1 mice at both d14 and d20 post-T." (PMID 21155838, 2011). "In the presence of chronic or repeated infections, CD4 and CD8 cells infiltrate in larger numbers than neutrophils, B cells and plasmacells do, and this recurrent inflammatory response is eventually responsible for the ultimate pathological effects in Ct infections." (PMID 22191045, 2011). "The 293T cells were then treated with CA-074Me at a lower concentration to see whether or not the CD4-independent vector infection would be promoted." (PMID 21541353, 2011). "We start by comparing T cell ELISPOT responses in patients acrossdifferent CD4 count strata, and then examine how the variation in these responsescorrelates with different patterns of selection across the HIV genome in patientswith very low CD4 cell counts compared with less progressed infections." (PMID 21544209, 2011). "In addition, conventional CD4+ T cells are the major source of IFN-γ a week after infection, starting its production at the same time as non-conventional CD4+ T cells." (PMID 21814579, 2011). "Future experiments in this system should take advantage of the ability to specifically deplete immune cell subsets (CD4+ cells, CD8+ cells, CD20+ cells, among others) to dissect the contributions of these various populations to immune protection conferred by vaccination and prior infection." (PMID 22102819, 2011). "A similar effect was observed after the transfer of CD4+T-cells obtained from FLU-NA-DIII vaccinated mice (P<0.05), whereas the transfer of FLU-NA-DIII immune CD8+T cells did not confer any protection against disease caused by infection with WNV-NY99." (PMID 21541326, 2011). "However, FV-specific CD4+ T cells only protect immunodeficient mice against acute disease, and all animals eventually succumb to the infection in the absence of CD8+ T cells and B cells." (PMID 21943070, 2011).
infection (continued). "Also the observation on coreceptor usage is limited by the absence of phenotypic/functional assays, patients' CD4 counts and clinical staging of the infection in the current study." (PMID 21423811, 2011). "However, dynasore treatment of CD4-expressing TE671 cells did not inhibit infection by the HIV-1 vector containing the HXB2 Env protein, consistent with previous reports." (PMID 22022555, 2011). "We first show that there is a threshold level of preservation of CD4+ T cells and a threshold viral load in the acute phase that correspond to the chronic phase thresholds of prolonged survival (for longer than 600 days) in CXCR4-tropic SHIV89.6P infection in rhesus macaques." (PMID 21359149, 2011). "Although CD4+ T cells and antibodies have been implicated in the control of VACV infection following systemic challenge, the cells responsible for preventing systemic spread of VACV following an intradermal infection have not been identified." (PMID 22102816, 2011). "However, our results provide the first evidence that CD4+CD25+FoxP3+ regulatory T cells (Treg), which have the capacity to suppress Th1 effector responses and favor Leishmania survival, are recruited to the infection sites in L. braziliensis-infected mice." (PMID 21390155, 2011). "However, compared with the mock-GRV-infected cells, the expression of full-length (FL) calpastatin-GRV in infected CD4+ T cells was not maintained, and the positive cells had almost disappeared by day 7 after infection." (PMID 22046434, 2011). "Thus, CD8 T cell responses (but not CD4 responses) are functionally compromised at day 8 p.i. in the absence of RANTES during LCMV clone 13 infection." (PMID 21814510, 2011). "On the other hand, CD4+ effector T cellsat the site of infection may not recognize or become activated optimally by APCsbearing M. tuberculosis-derived peptide:MHC II complexes, a processthat is required for IFN-γ production in peripheral tissues." (PMID 21637811, 2011). "Unaltered iATP in CD8+-cells and CD8+-cell counts in PML may reflect their physiologic role which comprises restraining the infection in the CNS in situ, but only secondarily after the initial immune response that occurs upon JCV antigen recognition by CD4+-cells and B-cells." (PMID 21533133, 2011). "Thus, despite priming for a Th17-cell response during subsequent infection, the protective effects of prior colonisation in this model was not dependent on CD4 cells but on rapid clearance of bacteria from the blood by antibody-mediated phagocytosis." (PMID 22003400, 2011). "Remarkably, and despite significant differences in immune activation and lymphocike production, percentages of peripheral CD4+ central memory T cells were markedly and reduced in both viruses in early infection, with no apparent differences detected before 21 days p.i between groups." (PMID 21464951, 2011). "Thus, both the N197S change and the gp41 changes contribute to the formation/exposure of the HR1 coiled coil on gp41, which in turn promotes the infection of CD4-negative cells expressing CCR5." (PMID 21731494, 2011). "Since cystatin C is not expressed in 293T cells, cystatin C may not be the factor necessary for the CD4-independent infection in 293T cells." (PMID 21541353, 2011). "This altered phenotype was widespread, occurring in each of the CD3+ populations (CD4+, CD8+, CD4−CD8−) and notably, was seen not only in those with active infection but in those who had eliminated the infection (CLInf), suggesting that this may lead to diminished effector cell function." (PMID 21559422, 2011). "The levels of CD4 cells producing IFN-γ, IFN-γ/TNF-α, or IFN-γ/TNF-α/IL2 all exceeded 1% in BCG vaccinated mice at week 2 of the P. yoelii infection (10 weeks post-BCG immunization) but declined at weeks 7 and 10 post-infection (15 and 18 weeks post-BCG vaccination)." (PMID 22205939, 2011).
infection (continued). "It is worth noting that the absence of αβ T cells did not result in compensatory increase of γδ T cells since less than 1% of CD4+ cells in I-Ab-/- mice expressed TCRγδ, a proportion similar to that of WT mice, and these percentages were not modified by the infection (data not shown)." (PMID 21814579, 2011). "Furthermore, in the absence of CD4 cells, no IL-17 was detected in the serum following infection of either colonised or control mice (data not shown)." (PMID 22003400, 2011). "Transcriptional analysis was performed on flow cytometry sorted subsets of naïve and central memory CD4+ T cells along with naïve CD8+ T cells on day 7 and 10 post infection, and compared with paired samples for the same subsets isolated at day 0, i.e., pre-infection." (PMID 22043290, 2011). "While exploring alternative CD4-dependent immune mechanisms targeting C. trachomatis in Irgm1/m3(-/-) mice, we identified an increase in the uterine population of cells expressing the neutrophil surface marker GR1 relative to wildtype mice at day15 post-infection." (PMID 21731484, 2011). "Furthermore, the frequencies of CD4+CD25+Foxp3+ Treg cells in the mLN and LP were comparable between WT and CD103−/− mice, both preceding and following infection." (PMID 21573179, 2011). "Therefore, in the current study we compared the two naïve CD4+ T-cell subsets within younger (20–32 years old) and older (39–58 years old) HIV-1 seropositive (SP) ART-naïve adults relatively early in infection, as well as with HIV-1 seronegative (SN) age-matched adults." (PMID 21298072, 2011). "The absence of productive infection was further confirmed by staining for intracellular p24 expression where we found that CCL19-treated infected CD4+ T-cells resulted in <1% p24-positive cells in contrast to IL-2/PHA activated infected CD4+ T-cells (mean p24 expression ~6-9%; n = 2)." (PMID 21992606, 2011). "Similarly large total numbers of lymphocytes, CD4+ T-lymphocytes, and CD8+ T-lymphocytes were detected in BALF after infection with WT, rSeV-luc(M-F*), or rSeV-luc(F-HN) virus, whereas mice inoculated with the attenuated rSeV-luc(P-M) had total lymphocyte counts only 10% as high." (PMID 21750677, 2011). "Thus, while one or more additional cell types may contribute to the pool of IL-10 observed during acute RSV infection, our results suggest that effector T-cells (both CD4+ and CD8+) may be a major source of IL-10 during human infection." (PMID 21829368, 2011). "The likelihood that Tax induces formation of a specialized cell adhesion synapse for efficient viral transmission is suggested by the result showing that a superantigen-induced immunological synapse between Jurkat cells and Raji/CD4 cells did not enhance cell-to-cell infection." (PMID 20195464, 2010). "Therefore, changes in CD4+ T cellrecruitment and related cytokines were not sufficient to modify negatively thecourse of infection in this model of experimental Influenza A virus infection." (PMID 21079759, 2010). "Early in infection, Nef removes mature CD4 molecules that are already present at the cell surface by enhancing their endocytosis by a pathway involving clathrin and AP2 followed by delivery of internalized CD4 to the multivesicular body pathway for eventual degradation in the lysosomes." (PMID 21176220, 2010). "Maraviroc blocked SIVsmm pseudotype infection of target cells expressing CD4 and smCCR5, reducing luciferase expression to the level seen with target cells expressing CD4 alone (data not shown), indicating complete blocking of smCCR5-mediated entry by maraviroc." (PMID 20865163, 2010). "However, in vitro the presence of anti-gC1qR mAbs (74,5,2 or 60,11) had no or little impact on the level of infection of purified CD4+ T cells by both CCR5- and CXCR4-tropic HIV strains." (PMID 20617170, 2010).